CSF1R (colony stimulating factor 1 receptor)
Diseases named in the same sentence as CSF1R in open-access papers (continued):
Sharing a sentence is not in itself a finding about the gene and the disease.
Leukoencephalopathy (continued). "Magnetic resonance imaging (MRI) features of CSF1R‐related leukoencephalopathy include ventricular enlargement, cerebral atrophy, periventricular calcifications, and thinning of the corpus callosum." (PMID 38922778, 2024). "CSF1R‐related leukoencephalopathy is characterized by a predominant involvement of microglia, classifying as microgliopathy." (PMID 38922778, 2024). "CSF1R-related leukoencephalopathy is therefore considered a primary microgliopathy of the central nervous system (CNS)." (PMID 37259140, 2023). "In conclusion, our data add evidence for allogenic hematopoietic stem cell transplant as a promising treatment in CSF1R-related leukoencephalopathy patients with slow to moderate disease progression." (PMID 37292133, 2023). "In this study, we report on two patients with CSF1R-related leukoencephalopathy in whom allogenic hematopoietic stem cell transplant at advanced disease stages led to clinical stabilization." (PMID 37292133, 2023). "This study thus helps unravel the pathological function of CSF1R deficiency in ALSP and provides therapeutic targets for alleviating microglial dysfunction associated with leukoencephalopathy." (PMID 37259140, 2023). "Significant clinical, radiological, and histopathologic overlap exists with CSF1R-related leukoencephalopathy, though there are some subtle differences." (PMID 37564735, 2023). "Extrapyramidal symptoms are less frequent but, if present, can serve as useful diagnostic clues, such as parkinsonism in CSF1R-related leukoencephalopathy, chorea in Gordon Holmes syndrome, and dystonia in AARS2-related leukoencephalopathy." (PMID 37564735, 2023). "Our results also indicate that microglial inhibition by minocycline can ameliorate behavioral impairment and ALSP pathogenesis in CSF1R-deficient male mice, suggesting a potential therapeutic target for CSF1R-related leukoencephalopathy." (PMID 37259140, 2023). "Multiple genes have been implicated in ALSP with the most common being the colony stimulating factor 1 receptor (CSF1R) gene and ALSP associated with CSF1R mutations have been subsequently termed CSF1R-related leukoencephalopathy (CRL)." (PMID 37333006, 2023). "CSF1R-related leukoencephalopathy (adult-onset leukoencephalopathy with axonal spheroids and pigmented glia, MIM # 221820) is a primary microgliopathy with autosomal-dominant inheritance, caused by a heterozygous pathogenic variant in CSF1R." (PMID 37564735, 2023). "Several studies have found that hematogenic stem cell transplantation is an effective disease modifying therapy however the literature regarding prodromal and early symptoms CSF1R-related leukoencephalopathy is limited." (PMID 35812083, 2022). "In line with this, the diseases are now summarized as CSF1R-related leukoencephalopathy and for the purposes of this review are collectively referred to as ALSP." (PMID 35185751, 2021). "The patient demonstrating a frontal-predominant MRI pattern had imaging features suggestive of CSF1R-related leukoencephalopathy, including periventricular calcifications seen on plain CT imaging that are highly suggestive of the disease." (PMID 33597917, 2021). "Colony-stimulating factor 1 receptor (CSF1R)-related leukoencephalopathy is a rare and rapidly progressive leukoencephalopathy characterized by cognitive, motor, and neuropsychiatric symptoms, which is often misdiagnosed." (PMID 33838643, 2021). "CSF1R is predominately expressed on microglia within the CNS and thus CSF1R-related leukoencephalopathy is considered as a primary CNS microgliopathy with dystrophic microglia playing a pivotal role in disease pathogenesis." (PMID 33731174, 2021). "Given that CSF1R mainly expresses in microglia, CSF1R-related leukoencephalopathy is representative of primary microgliopathies, of which microglia have a pivotal and primary role in pathogenesis." (PMID 34867307, 2021).
Leukoencephalopathy (continued). "The strong link between CSF1R mutations and pathologic microglia has resulted in further classification of CSF1R-related leukoencephalopathy as a CNS primary microgliopathy." (PMID 35185751, 2021). "Colony-stimulating factor 1 receptor (CSF1R)-related leukoencephalopathy is a rare and rapidly progressive leukoencephalopathy characterized by cognitive, motor, and neuropsychiatric symptoms." (PMID 33838643, 2021). "This review article introduces recent advances in microglial biology and CSF1R-related leukoencephalopathy." (PMID 33287883, 2020). "CSF1R is predominantly expressed on microglia within the central nervous system (CNS), and thus CSF1R-related leukoencephalopathy is now classified as a CNS primary microgliopathy." (PMID 33287883, 2020). "CSF1R is highly expressed on microglia within the central nervous system (CNS) and thus CSF1R-related leukoencephalopathy is considered to be a primary CNS microgliopathy." (PMID 33287883, 2020). "Since the numbers of non-classical monocytes can also be decreased with disease progression in CSF1R-related leukoencephalopathy patients, the clinical translation of pharmacological CSF1R inhibitors should be considered with caution." (PMID 33287883, 2020). "The focus of this study is on a series of patients with CSF1R-related leukoencephalopathy consistent with HDLS." (PMID 32430064, 2020). "Cux1 is a transcriptional factor associated with axonal projection and the numbers of Cux1+ neurons are reduced in CSF1R-related leukoencephalopathy patients compared to age-matched controls." (PMID 33287883, 2020). "This meaningful finding is further supported by a recent study convincingly showing the effectiveness of HSCT from human leukocyte antigen-matched wild-type CSF1R gene donors in two CSF1R-related leukoencephalopathy patients." (PMID 33287883, 2020). "A better understanding of specific microglial niches and their associated regulatory molecular pathways is thus necessary in order to effectively design microglial replacement therapies for CSF1R-related leukoencephalopathy patients." (PMID 33287883, 2020). "Strikingly, neurofilament light chain, a marker of axonal injury, can serve as a potential biomarker for CSF1R-related leukoencephalopathy as higher levels are evident in both the serum and cerebrospinal fluid of these patients compared to in MS patients." (PMID 33287883, 2020). "A higher proliferative rate of microglia in selective brain regions has also been noted in CSF1R-related leukoencephalopathy patients through pathological examinations." (PMID 33287883, 2020). "The age of disease onset in patients with CSF1R-related leukoencephalopathy varies from 10 to 78 years old with an average age of 43 years." (PMID 33287883, 2020). "Satisfactory long-term effects of HSCT on CSF1R-related leukoencephalopathy were noted in another case." (PMID 33287883, 2020). "It is important to note that there is no currently available, internationally used standardized and validated CSF1R-related leukoencephalopathy functional score scale." (PMID 33287883, 2020). "Individuals with CSF1R-related leukoencephalopathy variably present clinical symptoms including cognitive impairment, progressive neuropsychiatric and motor symptoms." (PMID 33287883, 2020). "The prevalence of CSF1R-related leukoencephalopathy is probably underestimated, but is gradually increasing mainly due to more widespread use of novel genetic tests such as next-generation sequencing." (PMID 33287883, 2020). "Potential therapeutic strategies by replacing microglia in order to improve the quality of life of CSF1R-related leukoencephalopathy patients will be presented." (PMID 33287883, 2020). "The functional role of infiltrating monocyte-derived cells in CSF1R-related leukoencephalopathy remains to be investigated." (PMID 33287883, 2020).
Leukoencephalopathy (continued). "Clinically, patients with CSF1R-related leukoencephalopathy typically manifest progressive cognitive decline, behavioral or personality changes and motor signs reminiscent of atypical Parkinsonism." (PMID 33287883, 2020). "Overall, Csf1r-deficient rodent models on specific genetic backgrounds provide useful information for exploring the pathophysiology of CSF1R-related leukoencephalopathy and potential treatments." (PMID 33287883, 2020). "Microglial distribution has been suggested to be regulated by CSF1R, and the uneven distribution of microglia in the CSF1R-related leukoencephalopathy brain supports this notion." (PMID 33287883, 2020). "Hyperintense signals of subcortical white matter in CSF1R-related leukoencephalopathy can rarely be extended to the cervical and thoracic spinal cord areas." (PMID 33287883, 2020). "It has recently been reported that CSF1R regulates microglial density and distribution in zebrafish, supporting our finding of altered microglial distribution in CSF1R-related leukoencephalopathy." (PMID 32430064, 2020). "Microglial replacement by infiltrating microglia-like cells thus provides an attractive possibility to remove dysfunctional microglia in patients with CSF1R-related leukoencephalopathy." (PMID 33287883, 2020). "The importance of sex-related differences in CSF1R-related leukoencephalopathy disease course requires further investigation." (PMID 33287883, 2020). "Although CSF1R-related leukoencephalopathy is a genetic disease inherited in an autosomal dominant pattern, approximately 36% of cases are sporadic." (PMID 33287883, 2020). "Pathological hallmarks of CSF1R-related leukoencephalopathy, also described as pigmented orthochromatic leukodystrophy (POLD), portray giant axonal swellings (spheroids), pigmented macrophages, loss of axons and myelin sheaths within the cerebral white matter." (PMID 31827782, 2019). "This study focused on Chinese patients with CSF1R-related leukoencephalopathy through detailed clinical, radiological, pathological and functional investigations." (PMID 31827782, 2019). "Persistent diffusion restriction can frequently be observed, which may distinguish CSF1R‐related leukoencephalopathy from other demyelinating diseases." (PMID 38922778, 2024). "Rare homozygous CSF1R mutations have been reported in children with leukoencephalopathy and almost complete absence of microglia, a phenotype also observed in Csf1r−/− mice." (PMID 39217398, 2024). "Mutations in CSF1R have been identified as a cause of a rare white matter disease called adult-onset leukoencephalopathy with axonal spheroids and pigmented glia (ALSP, also known as CSF1R-related leukoencephalopathy), characterized by progressive neurological dysfunction." (PMID 39031193, 2024). "Among microgliopathy, CSF1R-related leukoencephalopathy was the only one detected." (PMID 37564735, 2023). "Furthermore, for the first time we evaluate [18F] florbetaben, a PET tracer known to bind to intact myelin, as a novel MRI-adjunct tool to image white matter damage in CSF1R-related leukoencephalopathy." (PMID 37292133, 2023). "However, pCASL has seldom been used for imaging leukoencephalopathies and even less so for CSF1R-microglial encephalopathy." (PMID 35721475, 2022). "Moderate specificity for accurate diagnosis of CSF1R-related leukoencephalopathy relative to mutation-negative cases and the high specificity of CSF1R-related leukoencephalopathy relative to CADASIL cases were confirmed by this MRI diagnostic platform." (PMID 35185751, 2021). "In this paper, we discuss the dynamic analysis of a case of CSF1R-related leukoencephalopathy." (PMID 33838643, 2021). "CSF1R variants are associated with hereditary diffuse leukoencephalopathy (HDLS) with axonal spheroids and pigmented glia (ALSP), bvFTD, CBS, AD, multiple sclerosis, leukoencephalopathy (CADASIL) and PD." (PMID 33802612, 2021).
Leukoencephalopathy (continued). "Biallelic mutations in the AARS gene have been detected in approximately 20 patients with late-onset leukoencephalopathy who did not have a CSF1R mutation." (PMID 35185751, 2021). "The specificity of an MRI diagnosis for CSF1R-related leukoencephalopathy was determined by retrospective evaluation of 53 cases of CSF1R-mutation-negative leukoencephalopathy and 32 cases of CADASIL." (PMID 35185751, 2021). "Magnetic resonance imaging (MRI) signs and follow-up MRI of CSF1R-related leukoencephalopathy could help establish a diagnosis and thereby prevent misdiagnosis, but they are not widely known by neurologists." (PMID 33838643, 2021). "The patient was diagnosed with CSF1R-related leukoencephalopathy." (PMID 33838643, 2021). "Magnetic resonance imaging (MRI) signs and follow-up MRI of CSF1R-related leukoencephalopathy could help in establishing a diagnosis, but these features are not widely known by general neurologists." (PMID 33838643, 2021). "Therefore, ALSP is further divided into CSF1R- related leukoencephalopathy, AARS2- related leukoencephalopathy, and CSF1R/AARS2-negative ALSP." (PMID 34955818, 2021). "One study estimated the frequency of CSF1R-related leukoencephalopathy at 10% (5 of 48) of adult-onset leukoencephalopathies and suggested that it could be the most common type." (PMID 35185751, 2021). "Mutations in CSF1R, a key microglial specific gene which is associated with other leukoencephalopathies, has not been associated with MS pathology and sequencing of CSF1R in MS patients did not identify any relevant mutations." (PMID 32265902, 2020). "Artificial administration of neurotrophic factors such as BDNF may also be necessary when the microglial niche is made available during CSF1R-related leukoencephalopathy." (PMID 33287883, 2020). "This may also provide translational evidence for developing potential microglial sex-specific therapies for CSF1R-related leukoencephalopathy." (PMID 33287883, 2020). "Sex differences in CSF1R-related leukoencephalopathy: do microglia play a role?" (PMID 33287883, 2020). "Recent studies have described patients with homozygous CSF1R mutations causing a severe leukoencephalopathy with apparent congenital absence of microglia as well as skeletal dysplasia in some patients." (PMID 32430064, 2020). "Optic nerve damage and myelitis may also occur in patients with CSF1R-related leukoencephalopathy, which confounds the diagnosis." (PMID 33287883, 2020). "A combination of repopulation of microglia after depletion and bone marrow transplantation may serve as a novel therapeutic platform for CSF1R-related leukoencephalopathy." (PMID 33287883, 2020). "Furthermore, hematopoietic stem cell transplantation offers an emerging means of exchanging dysfunctional microglia with the aim of reducing brain lesions, relieving clinical symptoms and prolonging the life of patients with CSF1R-related leukoencephalopathy." (PMID 33287883, 2020). "Since microglia, the CNS-resident immune cells, are affected in this condition, developing immune cell-based therapies in order to improve disease prognosis and the quality of life of patients with CSF1R-related leukoencephalopathy represents a potential strategy to meet this urgent medical need." (PMID 33287883, 2020). "We propose that a combination of microglial replacement by the proliferation of resident microglia after depletion and other anti-inflammatory treatments that modulate the microenvironment may be more effective for CSF1R-related leukoencephalopathy." (PMID 33287883, 2020). "This suggests that microglia in CSF1R-related leukoencephalopathy retain the ability to proliferate, and that the reduction in their numbers might actually reflect reduced survival, given that CSF1R is important for microglial survival." (PMID 33287883, 2020). "This knowledge may provide valuable information in developing therapies targeting microglial functions beyond this rare familial CSF-1R-related leukoencephalopathy." (PMID 32430064, 2020).
Leukoencephalopathy (continued). "As the main differential diseases of CSF1R-related leukoencephalopathy, cerebral autosomal dominant arteriopathy with subcortical infarcts and leukoencephalopathy (CADASIL) and other leukoencephalopathies should be excluded with the help of pathological evidence and genetic detecting." (PMID 31827782, 2019). "Patients with CSF1R-related leukoencephalopathy have already been documented in Chinese Mainland." (PMID 31827782, 2019). "Thus, CSF1R‐related leukoencephalopathy is now considered a primary CNS microgliopathy." (PMID 38922778, 2024). "Retrospective application of these criteria to more than 150 patients with ALSP and CSF1R-positive mutations, CSF1R-negative leukoencephalopathies, or CADASIL showed a sensitivity of 99% to accurately detect probable or possible cases and an adequate specificity of 88% to exclude non-ALSP cases." (PMID 38529036, 2024). "Although microglial replacement by HSCT is far from perfect, allogeneic HSCT could be beneficial in patients with CSF1R-related leukoencephalopathy in clinical practice by providing brain-engrafting microglia-like cells with donor wild-type CSF1R to repopulate the microglial niche." (PMID 33287883, 2020). "This may help in identifying potential CSF1R-related leukoencephalopathy cases." (PMID 33287883, 2020). "However, these available preclinical results set the basis for further studies to explore how sex differences in human microglia might contribute to sex dependent phenotypic differences in CSF1R-related leukoencephalopathy patients." (PMID 33287883, 2020). "A defined CSF1R variant in one CSF1R-related leukoencephalopathy patient was associated with a progressive reduction in the frequency of circulating non-classical monocytes during disease course, since non-classical monocytes express the highest CSF1R levels." (PMID 33287883, 2020). "Therefore, understanding how to promote the mutant CSF1R phosphorylation may reveal new opportunities for targeted therapies and further investigations about the role of autophagy may shed light on the pathogenetic studies of CSF1R-related leukoencephalopathy." (PMID 31827782, 2019). "However, not all cases of leukoencephalopathy with neuroaxonal spheroids from an international biobank material carried CSF1R mutations, and until now no locus has been associated with the original Swedish HDLS (HDLS-S)." (PMID 31775912, 2019). "However, mutations in the CSF1-receptor (CSF1R) gene, a pivotal microglial-specific gene associated with other leukoencephalopathies, have not been correlated with MS pathology, as no relevant mutations were identified in CSF1R sequencing studies of MS patients." (PMID 38259497, 2023). "Both CSF1R- and AARS2-related leukoencephalopathy share several neurological symptoms and can present with similar white matter involvement, predominantly in the frontoparietal and periventricular regions." (PMID 35185751, 2021). "However, the numbers of microglia are significantly decreased in some but not all brain regions in patients, suggesting that signals involved in repopulating the microglial niche may be damaged in selective brain regions during CSF1R-related leukoencephalopathy." (PMID 33287883, 2020). "Thus, the cause of leukoencephalopathy in this patient is not likely to be this CSF1R variant." (PMID 30136118, 2018). "Similarly, both CSF1R- and AARS2-related leukoencephalopathy share several neurological symptoms and can present with similar white matter involvement, predominantly in the frontoparietal and periventricular regions." (PMID 40443872, 2025). "The model confirmed high sensitivity for probable or possible CSF1R-related leukoencephalopathy at 81%, but like many models, suffered from lack of specificity at 14%." (PMID 35185751, 2021). "Although there are no sex differences of CSF1R-related leukoencephalopathy in prevalence and disease duration, male patients develop disease significantly later than do females." (PMID 33731174, 2021).